IL6 (interleukin 6)
Diseases named in the same sentence as IL6 in open-access papers (continued):
Sharing a sentence is not in itself a finding about the gene and the disease.
cancer (continued). "The team tested the system by assaying the cancer biomarker human interleukin-6 (IL-6) and tackled issues such as the smartphone camera’s limited field of view (FOV), the non-uniform distribution of light across samples, and spectral crosstalk between channels." (PMID 29865250, 2018). "Therefore, our in vivo data suggested that USP24 regulated IL-6 expression not only affect the intravasation but also the extravasation of cancer cells." (PMID 30266897, 2018). "Data from studies of the bladder and other cancers implicate IL6, IL8, CXCL1, and PAI1 as factors that may play a role in the ability of the adipose CM and ASC CM to alter the migratory potential of the T24 cells." (PMID 29887999, 2018). "Treatment with IL-6 enhanced cancer cell migration, invasive and proliferation." (PMID 29348540, 2018). "Alternatively, sgp130, a natural inhibitor for IL-6 signaling could also be used for the inhibition of cancer growth." (PMID 29651420, 2018). "However, no data stated about the expression of sortilin in infiltrated-inflammatory cells as well as the implication of sortilin in the release of IL-6 from cancer cells." (PMID 30666202, 2018). "Likewise, our data for the first time identify IL-6 as a critical instigator of macrophage alternative activation in cancer." (PMID 29422647, 2018). "Interleukin (IL)-6 is a potent proinflammatory cytokine that exhibits functional pleiotropy in the regulation of growth, metastasis, and differentiation in numerous human cancers such as lung cancer, head and neck squamous cell carcinoma, breast, and PCa." (PMID 30333255, 2018). "IL-6 has previously been a target for cancer drug development." (PMID 30266897, 2018). "In general terms, TAMs exert procarcinogenic effects, either generating growth factors (Epidermal Growth Factor, Fibroblast Growth Factor and Vascular Endothelial Growth Factor) or releasing cytokines, such as IL-6, which exhibit anti-apoptotic activities on cancer cells." (PMID 29558948, 2018). "When the growth of cancer depends on IL-6 autocrine signaling, the IL-6 signal may be mediated by a mode of intracellular signaling and inhibitors of IL-6 signal transduction such as JAK inhibitors are possibly effective." (PMID 30423923, 2018). "To examine whether these cytokines have effects on cancer cells, we examined the proliferation of typical types of cancer cells cultured with various concentrations of recombinant IL-6, IL-12, and IFN-γ using an MTS assay." (PMID 30042824, 2018). "Moreover, UVB radiation causes increased ROS production and DNA damage, as well as a strong inflammatory response, characterized by the production of inflammatory cytokines, such as IL-6, which leads to premature skin aging and carcinomas." (PMID 30308980, 2018). "The most relevant pro-inflammatory cytokines contributing to the development of cancer cachexia and related with the metabolic alterations leading to muscle mass and adipose tissue wasting are interleukin-1, interleukin-6 (IL-6), tumor necrosis factor alpha (TNF-α), and interferon gamma." (PMID 29376055, 2017). "Of note, knock down of IL-6 did not cause any clear difference in growth rate of the cancer cells (data not shown)." (PMID 28515477, 2017). "Recently, our group described an important involvement of the immunoproteasome in cytokine-mediated inflammation in mice as inhibition of LMP7 alters differentiation into inflammatory effector cells and the release of pro-inflammatory cytokines such as IL-6, which plays a pivotal role in cancer." (PMID 28881611, 2017). "Therefore, we performed the first meta-analysis to evaluate IL-6-174G>C in predicting clinical outcomes of cancer." (PMID 28548958, 2017). "Not unexpectedly, we observed strong associations of high levels of factors such as IL-6, IL-8, FGF-2, and sIL-2Rα with poor clinical outcomes, consistent with documented reports for chronic inflammation and cachexia in multiple cancer types." (PMID 28938541, 2017).
cancer (continued). "In the current study, the deletion of Shp2-inhibited Erk phosphorylation and theIL-6-induced enhancement of cell migration and invasion, indicates that Shp2 may also act as a positive regulator in IL-6-signaling-mediated cancer progression." (PMID 28208810, 2017). "Thus, our bioinformatic analyses using the Oncomine and PrognoScan databases indicate that MUC2 and IL-6 expression are involved in cancer progression." (PMID 28725043, 2017). "IL-6 was initially thought to play a major role in immune and inflammatory responses, however IL6 abnormalities were found in many types of cancer, and some evidence showed that in cancer IL6 may play its downstream effects through JAK/STAT pathway." (PMID 28148898, 2017). "IL-6 has been previously shown as a growth-promoting factor for cancer cells." (PMID 28819126, 2017). "Importantly, a novel inhibitor of pathologic TLR3 signaling, phenylmethimazole (C10), has the ability to block IL-6 production, as well as decrease viability/growth and migration in these same cancers." (PMID 29371911, 2017). "Interleukin-6 (IL-6) is known to be involved in the pathogenesis of cancer progression." (PMID 28548958, 2017). "Therefore, TGF-β and IL-6 form an important paracrine signaling cycle between MFs and cancer cells, and this signal cycle contributes to cancer progression." (PMID 28819126, 2017). "The expression of IL6 is upregulated in cancer cells and serum in patients with CCA." (PMID 29029413, 2017). "The present study shows that the high levels of CTLA-4 and GARP, previously shown to be present on Tregs derived from human cancer ascites, may be directly induced by soluble factors within this ascites, and specifically IL-6." (PMID 29163543, 2017). "Interestingly, although other studies have shown a link between the overexpression of IL-6 and the promotion of cancer, our data showed that colonic IL-6 production is decreased in SAMP mice." (PMID 28301579, 2017). "To further confirm our hypothesis that EMT reversion leading to radioresistance reversion, we investigated the radioresistant cancer cells’ sensitivity to irradiation under the situation of EMT reversion by IL-6 pathway inhibition." (PMID 28061440, 2017). "IL-6 signaling plays a critical role in cancer stem cell phenotype." (PMID 28978005, 2017). "In contrast, cancer cell-CM or TGF-β stimulated MFs to produce IL-6." (PMID 28819126, 2017). "In this study, we investigated the effects of OPM2 (a MM cell line) exosomes (OPM2-exo) on regulating the proliferation, cancer-associated fibroblast (CAF) transformation, and IL-6 secretion of MSCs and determined the role of miR-21 and miR-146a in these effects." (PMID 29333170, 2017). "Given the current understanding that activation of STAT3 may also be the “hub” of the interplay among adipose tissue, inflammation, and cancer, our observations suggest that IL-6 may exert its “oncogenic” property through multiple pathways." (PMID 28077171, 2017). "Through this study, we have shown that the inhibition of the synergistic IL-6/8 signalling pathway reduces metastatic burden in mice, suggesting a potential strategy to prevent or treat cancer metastasis through the inhibition of tumour cell-density-dependent migration." (PMID 28548090, 2017). "This suggests that IL-6 trans-signaling might be a relevant target to halt the development of cancer cachexia." (PMID 28515477, 2017). "The role of IL‐6 in cancer‐related inflammation has been reviewed elsewhere." (PMID 28599100, 2017). "Accumulating evidences suggest SNPs in IL-6 which is crucial cytokine involved in several cellular pathways may affect survival of cancer." (PMID 28548958, 2017). "Consistent with this, short-term exposure of cancer-associated fibroblasts, mesenchymal stem cells, and osteoblasts to pH 6.8 promotes the expression of inflammatory and nociceptive mediators (NGF, BDNF, IL6, IL8, IL1b and CCL5)." (PMID 28903357, 2017).
cancer (continued). "Additionally, when knocking down the expression of ZEB1 in 4T1 cells, the invasive ability of cancer cells was similar with IL-6 signal inhibition." (PMID 29383101, 2017). "We found greater MDSC infiltration in cancer tissues with a high level of IL-6." (PMID 29326716, 2017). "MFs and MF-CM induced cancer cell proliferation, similar to the action of IL-6." (PMID 28819126, 2017). "Furthermore, some studies found that peritoneal infection increased serum interleukin-6 (IL-6), vascular endothelial growth factor (VEGF), and C-reactive protein (CRP) concentrations, which are associated with poor overall and cancer-specific survival." (PMID 27743072, 2017). "SphK blockage also suppressed VEGF, IL-8 and IL-6 secretion of the cancer cells." (PMID 29088837, 2017). "Importantly, treatment with MH also led to decreased interleukin-6 (IL-6) production by both cancer cell lines." (PMID 28856117, 2017). "Two hypotheses were suggested, IL-6 can either promote the secretion of angiogenic factors that might affect bevacizumab efficacy, or mediate VEGF secretion by cancer-associated fibroblasts (CAF)." (PMID 28927416, 2017). "IL-6 trans-signaling-dependent activation of STAT3 can drive cancer progression through the transcription of target genes including the cell cycle regulator cyclin D1, the proto-oncogene c-myc, transcriptional regulators such as JunB, cFos, C/EBPβ and C/EBPδ, and metabolic regulators such as mTORC1." (PMID 28676747, 2017). "IL-6 seems to have a broad range of effects on body metabolism and cancer." (PMID 28915665, 2017). "However, the accurate function of Shp2 in IL-6-signaling-promoted cancer development and progression, is largely undefined." (PMID 28208810, 2017). "We showed that MFs secrete IL-6 in response to factors secreted by cancer cells." (PMID 28819126, 2017). "Having the ability to detect the levels of IL-6 in blood can help diagnose cancer at early stages." (PMID 28420169, 2017). "In addition, elevated levels of IL-6 have been found in culture supernatant of cancer cells, especially, multidrug resistant cell lines and CSCs enriched culture." (PMID 28927416, 2017). "Thus, IL-6 is considered a prognostic marker and current anti-cancer therapies already target IL-6 activity." (PMID 28030810, 2017). "Our study also highlights the effect of constitutively higher IL-6 expression in cancer prognosis." (PMID 28548958, 2017). "Furthermore, we present evidence that UHRF1 deficiency leads to the induction of EMT by activating the CXCR4/AKT-JNK/IL-6 signaling pathway, thereby contributing to the expansion of cancer stem-like cells." (PMID 28584306, 2017). "Interestingly, IL-6 is known to activate STAT3 which in turn interacts with NF-κB to form ReLA survival complex that gives the radio resistant property to cancer cells." (PMID 29070894, 2017). "Elevated circulating levels of IL‐6 are an indicator of a poor outcome in several cancer entities." (PMID 28599100, 2017). "The inflammatory cytokines released by immune cells in response to the presence of the cancer, such as interleukin-1β(IL-1β), interleukin-6 (IL-6) and tumor necrosis factor-α (TNF-α), have been shown to play a key role in the disturbances of appetite and body weight control." (PMID 29207625, 2017). "We also found that cancer cells and cancer-CM promoted IL-6 secretion by MFs." (PMID 28819126, 2017). "Notably, as the major inflammation mediator, IL-6 is a dominant activator of STAT3 to promote cancer progression." (PMID 28036277, 2017). "High-sensitivity C-reactive protein (hsCRP) and interleukins 6 and 10 (IL-6, IL-10) have been associated with low level HIV viremia and reported as predictors of noninfectious complications including cardiovascular disease (CVD), cancer and overall mortality." (PMID 28830393, 2017). "MUC2 and IL-6 were localized in the cytoplasm of the cancer cells." (PMID 28725043, 2017).
cancer (continued). "Neutralizing antibodies to IL-6 or histone H3 or knockout of the receptor for advanced glycation end products all limit K-Ras signaling activation, prevent cancer development and metastasis/invasion, and prolong animal survival in Pdx1-Cre;K-RasG12D/+;Hmgb1−/− mice." (PMID 28374746, 2017). "An elevated activation of IL-6 signaling has been observed in many types of cancer." (PMID 28208810, 2017). "Furthermore, Oligo-Fucoidan supplementation increases cancer cell death and attenuates the adverse effects induced by etoposide that decreases production of the pro-inflammatory cytokine IL-6 and chemokine CCL2/MCP-1." (PMID 28928376, 2017). "Targetting IL-6 signaling pathway may be a promising clinicaltherapeutic strategy in cancer treatment." (PMID 28659496, 2017). "In cancer stem cells studies, IL-6 has been considered as a key regulator on CSCs self-renew." (PMID 28927416, 2017). "Therefore, it is the key step for the formation of hexamer and cancer cell proliferation and migration that IL-6 binds to GP130." (PMID 28430601, 2017). "Elevated IL-6 and IL-6-mediated activation of STAT3 have been reported to cause chemoresistance to several chemotherapeutic drugs, like cisplatin and taxol, in various cancers including OCs." (PMID 29050266, 2017). "Our results, together with these recent in vivo studies could suggest that development of cancer cachexia might be prevented by compounds that either restrict IL-6 trans-signaling or interfere with autophagy." (PMID 28515477, 2017). "Based on this conclusion, it is highly possible that NTP could be a promising therapy for cancer related with IL-6 signaling." (PMID 28801613, 2017). "In a murine study mimicking excessive IL-6 as seen in chronic inflammatory disorders and several cancers, T cells isolated from peripheral lymphoid organs in IL-6 transgenic mice not only had increased levels of Th17 but also Tregs which further were shown to have retained suppressive activity." (PMID 29163543, 2017). "TAM count was significantly correlated with Treg count and with IL6-positive cancer cell count." (PMID 29048388, 2017). "inhibited HDAC3 to decrease the level of IL-6 produced by the cancer cells." (PMID 29254283, 2017). "Elevated serum levels of IL-6 have also been shown to negatively correlate survival of cancer patients, which might be attributed to defective responses of patients T cells to IL-6." (PMID 28650989, 2017). "Our findings suggests that the IL-6/STAT3 signaling pathway activated by CAFs could be a promising target for anti-cancer therapies." (PMID 29100297, 2017). "Numerous studies have suggested that polymorphisms in genes encoding inflammatory response factors, such as TNF-alpha -308G>A, IL6 -174G>C, and NFKBIA -826C>T may contribute to cancer susceptibility." (PMID 28039461, 2017). "IL-6 is a critical link between inflammation and cell transformation in mammary tissue, and IL-6 signaling in cancer cells results in EMT phenotypes that facilitate cancer cell invasion into the surrounding tissue and blood vessels, and cause distant metastasis." (PMID 27609180, 2016). "Indeed, in cancer inflammatory environment, IL-6 induces dimerization of IL-6 receptors, leading to activation of STAT353." (PMID 26888313, 2016). "IL-6 is a pleiotropic cytokine, which plays important roles in the pathophysiology of cancer." (PMID 27248826, 2016). "Besides, IL-6 has been reported to stimulate directional migration and invasion of human cancer cells." (PMID 27851822, 2016). "Pharmacological and molecular inhibitions of HDAC3 decreased IL-6 levels in cancer cells." (PMID 26745602, 2016). "Moreover, in cancer cells that have metastasized to bone, LPA signaling can promote osteolysis by inducing cancer cell production of cytokines, such as IL-6 and IL-8, which can stimulate osteoblasts to secrete RANKL, a key promoter of osteoclastogenesis." (PMID 27571113, 2016).
cancer (continued). "The influence of IL-10 on more severe cancer disease is explained by antagonistic effect of IL-10 on the formation of pro-inflammatory cytokines (IL-6, TNF, IL-1α, IL-1β, IL-12) and inhibition of the inflammatory response, which plays an important role in the development of cancer." (PMID 27547238, 2016). "Also, osteopontin appears to act in a feed-back loop with cancer cells, stimulating their proliferation, as well as adipocytes, where osteopontin stimulates the synthesis of inflammatory cytokines such as IL-6 and TNFα." (PMID 27049717, 2016). "IL-6 is a cytokine that was discovered in the 1980s and is produced by several types of cells from the innate immune system, as well as by other cells including those from several types of cancer." (PMID 27129274, 2016). "Secretion of cytokines and chemokines, such as IL-6 and IL-8, are of significance for a sustained inflammatory response; these mediators have also been suggested to play an important role in the development of different types of cancers, among them PCa." (PMID 27284286, 2016). "Among several chemokines, CCL1, −2, −4, −5, −7, −8, −12, −13, and IL6 might influence the interaction of inflammation with cancer malignancy, and CCL2, −3, −5, −7, CXCL12, −14, and IL6 were found to be able to affect the macrophage infiltration." (PMID 26790618, 2016). "IL-6 contributes to the chronic liver inflammation that leads to cancer." (PMID 27043586, 2016). "IL-6 can also be synthesized, expressed, and secreted by cancer cells, except inflammatory cells." (PMID 27174914, 2016). "Indeed, the overproduction of IL-6 is commonly encountered in a variety of cancer cells and elevated serum IL-6 levels correlate with poor outcome in cancer patients." (PMID 27190500, 2016). "The findings from the studies above implicate a role of IL-6 in the progression of cancer pain." (PMID 27267059, 2016). "In contrast, IL-6 inhibition by siRNA reverted these malignant phenotypes in cancer cells." (PMID 27732936, 2016). "Interestingly, decreased actin polymerization by LDE225 was partially reversed by rhSDF-1 or rhIL-6, suggesting that SDF-1 or IL-6 secreted by BMSCs played an important role in cancer cell migration and adhesion." (PMID 26885608, 2016). "Considering the importance of IL-6 signaling in inflammation and cancer development, several monoclonal antibodies targeting IL-6 or IL-6R have been developed as therapeutic agents for various inflammatory diseases and cancers." (PMID 27080032, 2016). "Furthermore, several lines of evidence implicate IL-6 as a promoting factor in cancer and suggest that IL-6 contributes to a chronic inflammatory and tumorigenic microenvironment in CRC." (PMID 27738330, 2016). "Moreover, IL6 produced by TAMs promoted cancer stem cell expansion and the expression level is proportional to the HCC clinical stages." (PMID 27270308, 2016). "However, routine measurement of IL-6 in cancer patients in the clinical setting is expensive and inconvenient." (PMID 27650456, 2016). "Hyper-IL-6, an artificial fusion cytokine comprising IL-6 plus an artificial linker with the soluble IL-6 receptor, has been utilized as a component of whole cell vaccines against cancers." (PMID 27071457, 2016). "Furthermore, PTEN can promote host immune response against cancer cells by repressing the expression of immunosuppressive cytokines IL-10, IL-6, and VEGF and programmed cell death 1 ligand (PD-L1) in a PI3K/AKT pathway-dependent manner." (PMID 27391071, 2016). "On the other hand, other works support the hypothesis that proinflammatory factors, such as IL-6, may positively contribute to the abnormal angiogenesis in cancer." (PMID 27929540, 2016). "We next examined if upregulated MMP-14 by IL-6 contributes to promoting cancer dissemination." (PMID 27531896, 2016).